SLAIN2 (SLAIN family member 2)
Description:
Binds to the plus end of microtubules and regulates microtubule dynamics and microtubule organization. Promotes cytoplasmic microtubule nucleation and elongation. Required for normal structure of the microtubule cytoskeleton during interphase.
Synonyms: KIAA1458; FLJ21611
Tractability: PROTAC: ubiquitination databases record sites on it; its protein half-life has been measured.
Gene: Protein-coding gene on chromosome 4 (48,341,472 to 48,426,201, forward strand). Ensembl gene ENSG00000109171.
Subcellular location: Cytoplasm, cytoskeleton
Subcellular location (Human Protein Atlas): Centrosome; Cytosol; Basal body; Primary cilium tip
Gene Ontology:
Molecular function: protein binding
Biological process: cytoplasmic microtubule organization; microtubule nucleation; positive regulation of microtubule polymerization; regulation of microtubule polymerization
Cellular component: centrosome; ciliary basal body; ciliary tip; cytosol; microtubule cytoskeleton; microtubule plus-end; cytoskeleton
Genetic constraint (gnomAD): Loss-of-function variants: 30 observed, 48.26 expected, observed/expected ratio (o/e) 0.62, 90% interval 0.46 to 0.84. The synonymous counts are far from expectation, so gnomAD's model fits this gene poorly and the ratio says little. Missense variants: 755 observed, 688.71 expected, observed/expected ratio (o/e) 1.1, 90% interval 1.03 to 1.16. Synonymous variants: 310 observed, 250.88 expected, observed/expected ratio (o/e) 1.24, 90% interval 1.12 to 1.36.
Homologues: Orthologues: chimpanzee SLAIN2 (99% identical), macaque SLAIN2 (99% identical), rabbit SLAIN2 (98% identical), pig SLAIN2 (97% identical), dog SLAIN2 (96% identical), rat Slain2 (96% identical), mouse Slain2 (94% identical), guinea pig SLAIN2 (93% identical), tropical clawed frog slain2 (66% identical), zebrafish slain2 (59% identical). Paralogues in human: SLAIN1 (34% identical).
Diseases named in the same sentence as SLAIN2 in open-access papers:
SLAIN2 is named in the same sentence as 6 diseases in open-access papers, as found by Europe PMC text mining. Sharing a sentence is not in itself a finding about the gene and the disease. The quoted sentences say what the papers report.
glioma (1 paper, 2023). A benign or malignant brain and spinal cord tumor that arises from glial cells (astrocytes, oligodendrocytes, ependymal cells). "TTBK2, NAV1, and CTTNBP2 were considered as protective factors, while SRCIN1, TRIO, KIF18A, and SLAIN2 were risk factors for glioma." (PMID 36979179, 2023). "Moreover, TTBK2, NAV1, and CTTNBP2 were protective factors for glioma, while SRCIN1, TRIO, KIF18A, and SLAIN2 were risk factors." (PMID 36979179, 2023). "Our study found that compared with normal tissues, CTTNBP2, KIF18A, NAV1, SLAIN2, and TRIO were upregulated in glioma, while SRCIN1 and TTBK2 were downregulated." (PMID 36979179, 2023). "Compared with the normal samples, except for SLAIN2, the CTTNBP2, KIF18A, NAV1, and TRIO protein expression in glioma was elevated, while SRCIN1 and TTBK2 were decreased." (PMID 36979179, 2023).
Insulin resistance (1 paper, 2023). Increased resistance towards insulin, that is, diminished effectiveness of insulin in reducing blood glucose levels. "Putative GSK3 substrates with defective dephosphorylation in insulin resistance included S520 and S553 on PHLDB1; S350, S354, and S358 on the microtubule regulator SLAIN2; and S1036 on ASK1." (PMID 36808134, 2023).
mammary cancer (1 paper, 2019). "The SLAIN2 FS was present in the 4T1 mammary cancer cell line, but ZDHHC17 FS was not." (PMID 31578439, 2019).
cancer (3 papers, 2020 to 2023). A tumor composed of atypical neoplastic, often pleomorphic cells that invade other tissues. "Collectively, these results provide new insight into the centrosomal functions of SLAIN2 and the molecular defects underlying cancer associated with deregulation of SLAIN2." (PMID 32256142, 2020). "SLAIN2 is a microtubule plus-end tracking protein implicated in cancer." (PMID 32256142, 2020). "Increased SLAIN2 expression encourages the invasion of mesenchymal cells in three-dimensional culture and mouse cancer models." (PMID 36979179, 2023). "Among the centrosome proteins proximate to SLAIN2, several functional modules stand out by their link to cellular processes that go awry in cancer." (PMID 32256142, 2020). "Although these studies provided new insight into the control of microtubule plus end dynamics in cells and in cancer, the centrosomal functions and mechanisms of SLAIN2 remain unknown." (PMID 32256142, 2020). "Despite this, SLAIN2 strongly stimulated processive MT polymerization in interphase cells and, in a murine cancer model, it is essential for mesenchymal cell invasion in 3D culture while, in rats, SLC10A4 is expressed by cholinergic neurons even if it is not reported as choline transporter." (PMID 32784482, 2020). "Moreover, SLAIN2 and CLASP1 together suppress catastrophes and are essential for mesenchymal cell invasion in 3D culture and in a mouse cancer model." (PMID 32256142, 2020).
tumor (2 papers, 2019 to 2023). "When tested as gene vaccines in the mouse tumor injection model of 4T1, SLAIN2-FS conferred tumor retardation but ZDHHC17 did not." (PMID 31578439, 2019).
SLAIN2 also shares sentences with these, for which no sentence is quoted: osteosarcoma (1 paper).